NTN1 (netrin 1)
Diseases named in the same sentence as NTN1 in open-access papers (continued):
Sharing a sentence is not in itself a finding about the gene and the disease.
tumor (continued). "Based on data from 10,437 subjects with 33 types of solid tumors in The Cancer Genome Atlas, we systematically analyzed the tumor molecular biological characteristics of NTN1 and its receptors through bioinformatics." (PMID 41407823, 2025). "The role of Netrin-1 is context-dependent: it fosters tumor progression in chronic inflammation through DCC pathway upregulation but has also been implicated in glioma cell motility inhibition." (PMID 40243726, 2025). "We also analyzed the correlation between the expression of NTN1 and its receptors and 6 types of tumor-infiltrating immune cells using the TIMER database." (PMID 41407823, 2025). "Another significant result of this study suggested that NTN1 and its receptors can be used as potential targets for tumor immunotherapy." (PMID 41407823, 2025). "Co-immunofluorescence showed that NTN1+ tumor cells co-expressed phosphorylated ERK in PanIN lesions from KC mice." (PMID 40777309, 2025). "In contrast to Netrin-1, Netrin-4 serves as a tumor suppressor in CRC by inhibiting angiogenesis, hinders primary tumor growth, liver and lung metastases." (PMID 38081962, 2024). "NTN1 gene expression was also found to be a positive predictive sign for local tumour recurrence in Cox regression models." (PMID 38546656, 2024). "Lastly, Netrin-1 and –3 histochemical staining confirms its presence in the local tumor microenvironment." (PMID 39023520, 2024). "The proportion of tumour cells following anti-netrin-1 treatment was 3.19 times lower after two cycles of NP137." (PMID 37532934, 2023). "Netrin-1 was upregulated in mouse tumours following deletion of Pten, and this upregulation was decreased following NP137 treatment." (PMID 37532934, 2023). "The aim is to evaluate the efficacy of restoring apoptosis in tumor cells, using the first-in-class humanized monoclonal antibody that blocks Netrin-1 (NP137) alone or combined with an anti-PD-1." (PMID 37046702, 2023). "Our results identify netrin-1 blockade as a clinical strategy triggering both tumour debulking and EMT inhibition, thus potentially alleviating resistance to standard treatments." (PMID 37532934, 2023). "To gain insight into the underlying mechanisms that link netrin-1 blockade to tumour growth inhibition we first analysed, based on the hypothesized mode of action of netrin-1 blockade, whether tumour growth inhibition was associated with tumour cell death in Pten f/f tumours treated with NP137." (PMID 37532934, 2023). "In vivo mouse sciatic nerve model also demonstrated that overexpression of NTN1 to a great extent offset the inhibitory effect of sh-DIAPH2-AS1 on the growth of tumor, and NTN1 knockdown repressed the tumor growth accelerated by DIAPH2-AS1 overexpression." (PMID 37037818, 2023). "PLAC1 and Netrin-1 can become important markers for judging tumor metastasis, and can also be potential targets for the treatment of CRC." (PMID 37568074, 2023). "Upregulation of NTN1 also promotes the growth of various tumor cells, such as melanoma, breast cancer, and liver cancer; the function of NTNG1 is to increase the migration of ovarian cancer cells." (PMID 37345154, 2023). "We thus treated control and Pten-deleted mice for 3–4 weeks with NP137 (10 mg kg–1, three times per week) and analysed netrin-1 expression and tumour progression." (PMID 37532934, 2023). "The aberrant expression of the axon guidance factor, netrin-1, is observed in various types of malignancies, and it participates in the proliferation and apoptosis of tumor cells." (PMID 37038247, 2023). "It has been associated with the development of a variety of tumors, including through tumor suppression, and has also been shown to promote apoptosis independently of Netrin-1." (PMID 36292695, 2022). "On the other hand, Netrin-1 is also involved in the regulation of the biological behavior of tumor cells." (PMID 36093435, 2022).
tumor (continued). "Intriguingly, the molecular mechanisms behind many of the developmental, physiological, and tumor-promoting functions of netrin-1 remain poorly characterized." (PMID 33883596, 2021). "Particularly, the expression of the Netrin-1 protein in GBM has been considered relevant in the promotion of tumor angiogenesis." (PMID 34361013, 2021). "NTN1, although expressed by tumor cells, is mostly located either in adjacent endothelial cells or stroma, suggesting a relevant contribution to this pathology acting as chemotactic molecule." (PMID 33724150, 2021). "UNC5B is a netrin-1-dependent receptor that participates in axonal migration and angiogenesis by binding to netrin-1, which exerts its function in tumor suppression." (PMID 32596158, 2020). "Overall, netrin-1 plays a crucial role in regulating acute/chronic inflammation, angiogenesis, and tumor and EC invasiveness." (PMID 30532711, 2018). "Netrin-1, a chemoattractant factor in the neuronal system, promotes tumor progression by enhancing angiogenesis and metastasis." (PMID 30532711, 2018). "We implanted either wild type or cells expressing either NTN1FH or NTN1(II)FH peptide into mice brains and followed the tumor growth similarly to U87MG xenografts." (PMID 28069038, 2017). "Western blotting analysis revealed that netrin-1 expression was higher in 87.5% (14/16) of tumor tissues compared with their paired adjacent normal tissues (n = 16, p = 0.043)." (PMID 28710382, 2017). "In all tumor types NTN1 was localized to hypoxic tumor areas and vasculature including glomerular vessels." (PMID 28069038, 2017). "Netrin-1 knockdown reduced cell proliferation and attenuated tumor growth in a xenograft mouse model." (PMID 28710382, 2017). "In GBM tissues NTN1 expression was enriched to areas surrounding the necrotic tumor core and especially to pseudopalisade structures." (PMID 28069038, 2017). "We observed that in the NTN1 expressing U87MG xenografts tumors the boundary of the tumor and the normal brain tissue was positive for stemness indicating marker nestin." (PMID 28069038, 2017). "We further stained the NTN1FH tumor sections for nestin and HA to localize NTN1 positive cells in the tumors." (PMID 28069038, 2017). "Recent research into tumors reveals that Netrin-1 is also involved in the inhibition of tumor cell apoptosis." (PMID 29321724, 2017). "Deleted in colorectal carcinoma (DCC) constrains tumor progression by inducing apoptosis unless engaged by its ligand netrin-1 in breast and colorectal cancers." (PMID 27398102, 2016). "The impact of netrin-1 on tumor progression is further complicated by its roles in angiogenesis, as both attractive and inhibitory effects on the extension of blood vessels have been documented." (PMID 27034160, 2016). "We showed that netrin-1 inhibited PDAC tumor growth by interfering with integrin β4 expression, which depends on the activation of UNC5b/FAK signaling and requires NO-mediated PP2A activation and the subsequent suppression of the MAPK pathway." (PMID 27034160, 2016). "Combination of decitabine with NTN1 silencing strategies or with an anti‐netrin‐1 neutralizing antibody potentiates tumor cell death and inhibits tumor growth in different animal models including patient‐derived xenografts." (PMID 27378792, 2016). "In the present study, we found that netrin-1 expression was decreased in stage I/II PDAC samples, and demonstrated that netrin-1 suppressed the tumor-forming ability of PDAC cells." (PMID 27034160, 2016). "Integrin β4 expression was reduced following netrin-1 stimulation and mediated, at least in part, the observed tumor-inhibitory effect of netrin-1." (PMID 27034160, 2016). "To investigate the mechanism by which netrin-1 inhibits PDAC tumor growth, we examined the control and netrin-1-over-expressing MiaPaCa II cells for their potential differences in proliferation, apoptosis, and adhesion ability." (PMID 27034160, 2016).
tumor (continued). "All these data suggest that inactivation of netrin-1 and overexpression of netrin-4 can be useful in tumor therapy." (PMID 25143950, 2014). "The multifunctional molecule netrin-1 is upregulated in various malignancies and has recently been presented as a major general player in tumorigenesis leading to tumor progression and maintenance in various animal models." (PMID 24647424, 2014). "Netrin-1 was mainly localized in tumor cell cytoplasms, bound to tumor cell membranes or found within tumor cell nuclei." (PMID 24647424, 2014). "The netrin-1 upregulation, observed in various cell lines and tumours with different cytotoxic drugs, suggests that this upregulation is rather related to a general survival stress response than to a specific alteration of a specific pathway." (PMID 24293316, 2013). "As a consequence, we show that combination of Doxorubicin with a netrin-1 interfering drug candidate potentiates tumour growth inhibiting effect in an animal model." (PMID 24293316, 2013). "Targeted therapies aiming to trigger tumour cell death via netrin-1/receptors interaction interference are under preclinical evaluation." (PMID 24293316, 2013). "Increased NTN1 mRNA levels correlated with advanced tumor stage (stage III, n = 8, 100%) and grade (grade 3, n = 7, 100%)." (PMID 21789787, 2011). "NTN1 and its receptors can be used as potential targets for tumor immunotherapy." (PMID 41407823, 2025). "NTN1 overexpression shortened mouse survival and increased histological tumor areas in the liver." (PMID 40777309, 2025). "Studies indicate that netrin-1 expression in GBM promotes tumor angiogenesis." (PMID 40723793, 2025). "NTN1 promotes innervation and tumor cell growth of PDAC liver metastases." (PMID 40777309, 2025). "Nevertheless, the mechanism of NTN1 upregulation during carcinogenesis and its role in tumor innervation remain unknown." (PMID 40777309, 2025). "Therefore, the NTN1/α6β4/UNC5C signalling pathway is critical for regulating tumour growth and metastasis." (PMID 38546656, 2024). "In addition, the combination of decitabine and NTN1 accentuated tumour cell death and effectively restraint of tumour development in animal models." (PMID 38546656, 2024). "Additionally, treatment with the NTN1‐interfering antibody slowed down tumour growth and increased survival in lymphoma mouse xenograft models." (PMID 38546656, 2024). "Netrin-1 exhibits both pro- and anti-tumor functions in PDAC." (PMID 38081962, 2024). "Fusion NTN1::CDRT15P2 was found expressed in both tumor cell clusters and more likely clonal." (PMID 38464114, 2024). "Consequently, either losing receptor activity or increasing NTN1 expression is advantageous for tumour progression." (PMID 36831381, 2023). "Due to the potential contribution of dysregulated adipokines in tumour development, the effect of the secretome of adipocytes obtained from patients with OB on the expression levels of the main receptors of NTN-1 was investigated in both HT-29 and Caco-2 cell lines." (PMID 36831381, 2023). "NTN-1 has been identified as a direct target of the transcription factor nuclear factor κ B (NFκB), strengthening its involvement as a mediator between inflammation and tumour development." (PMID 36831381, 2023). "For example, the expression of the truncated ΔN-netrin-1 (nucleolar N-terminal truncated isoform of netrin 1) was found to drive rDNA transcription and pre-rRNA processing and to increase the number of mature ribosomes in tumor cells, promoting the malignant phenotype." (PMID 35559034, 2022). "Recently, the presence of axonal guidance molecules within exosomes released by tumor cells has been described, which would suggest that Netrin-1 could be released as well as contained within these microvesicles." (PMID 34361013, 2021).
tumor (continued). "Furthermore, it would be necessary to determine if the Netrin-1 concentration in exosomes derived from GBM cells is higher than in exosomes released by other cell types present in the tumor microenvironment, such as astrocytes." (PMID 34361013, 2021). "This review will describe in greater depth the role of Netrin-1 in the neovascularization process, the signaling pathways that could regulate its expression, and how this protein could be participating in the tumor microenvironment of GBM." (PMID 34361013, 2021). "Therefore, preclinical and clinical studies should be planned to investigate the therapeutic potential of the Netrin-1/CD146 pathway in tumor angiogenesis." (PMID 32782280, 2020). "This triggered the death of NTN1 expressing tumor cells in vitro." (PMID 30923634, 2019). "Since the downregulation of netrin-1 has shown to reduce metastasis or tumor growth in multiple cancers, our study sought to investigate whether netrin-1 is also a promising target in mRCC." (PMID 29854303, 2018). "In addition, NF-κB has also been reported to confer a selective advantage for tumor development through up-regulation of netrin-1 expression in colorectal cancer." (PMID 28710382, 2017). "Moreover, approximately 70% of the tumor cells stained positively for the netrin-1 protein in immunohistochemistry (IHC), whereas positive staining of netrin-1 in normal brain cells was hardly observed." (PMID 28710382, 2017). "Furthermore, NTN1 expression increased tumor growth and altered the growth into more invasive phenotype." (PMID 28069038, 2017). "Furthermore, the border of tumor stroma and the normal mouse brain tissue was clear-cut in the control and NTN1(II)FH tumors but more diffuse in NTN1FH tumors." (PMID 28069038, 2017). "In orthotopic xenograft models, the expression of NTN1 increased the total tumor mass." (PMID 28069038, 2017). "Moreover, NTN1 silencing was sufficient to induce tumor growth inhibition following DAC monotherapy." (PMID 27378792, 2016). "Nevertheless, one can in contrast hypothesize that potentially lower rates of secreted netrin-1 as a result of sorafenib treatment may improve netrin’s neutralization rates and therefore further affect global survival of the tumor." (PMID 28174720, 2016). "A tumor-suppressive role of netrin-1 was also observed in several other types of tumor cells." (PMID 27034160, 2016). "In addition, the tumor growth curves were delineated by measuring the tumor volumes of the xenografts in the nude mice, and a successive 28-day examination showed a sustained lag in the tumor growth of the netrin-1-over-expressing cells." (PMID 27034160, 2016). "Netrin-1 affects caspase-3 activity in certain tumor cells and inhibits apoptosis." (PMID 27034160, 2016). "Furthermore, a combination of decitabine with NTN1 silencing strategies or with an anti‐netrin‐1 neutralizing antibody potentiates tumor cell death and efficiently blocks tumor growth in different animal models." (PMID 27378792, 2016). "These treatments killed netrin-1-expressing tumor cells both in vitro and in vivo." (PMID 25950466, 2015). "Like Ntn1, Ntn4 is able to stimulate tumor proliferation and angiogenesis." (PMID 25909166, 2015). "We also assessed MUC4 and netrin-1 expression in tumor tissues from nude mice." (PMID 26393880, 2015). "In addition, netrin-1 or netrin-4 overexpression in tumor cells delays tumor angiogenesis in various animal models." (PMID 25853509, 2015). "Additionally, we focally observed a regional hierarchy of nuclear netrin-1 signal, which was most prominently seen adjacent to the fibrovascular tumor stroma." (PMID 24647424, 2014). "Additionally, also the subgroup of NSCLC brain metastases demonstrated significantly reduced patient survival rates in case of high netrin-1 levels in tumor cells." (PMID 24647424, 2014).
tumor (continued). "Of interest, Doxorubicin treatment (i.p.)is associated with upregulation of netrin-1 in the xenograted tumours but not in tissues such as the heart, lung, intestine or kidney." (PMID 24293316, 2013). "To further analyse whether conventional drug treatments trigger tumour-specific increased netrin-1 level in human patients, we looked for pathologies where human tumours are sampled from the same patient before and after conventional treatments." (PMID 24293316, 2013). "Moreover, it has been shown that netrin-1, through its canonical receptors stimulates tumor growth and metastasis." (PMID 22761819, 2012). "In a similar way – and considering that netrin-1 is pro-angiogenic – our results allow speculatation that ADORA2B could mediate the sprouting of vessels during tumor neovascularization." (PMID 18447899, 2008). "The receptor/netrin-1 pairs may indeed limit tumour development by inducing apoptosis of cells that have acquired transforming capacities." (PMID 15956977, 2005). "Moreover, the correlation between high NTN1 expression and tumour stage and grade suggests that NTN1 may perform an oncogene role in OC." (PMID 38546656, 2024). "In PDAC, perineural infiltration is present in early and late stages of the disease and neuronal infiltration by tumor cells may contribute to pain and tumor progression indicating Netrin-1/Adora2b signaling could be evaluated as a therapeutic strategy to reduce perineural infiltration." (PMID 37187740, 2023). "Netrin-1 promotes proliferation, migration, and adhesion of vascular endothelial cells and smooth muscle cells, and its pro-angiogenic effects may be necessary for tumor growth." (PMID 37568074, 2023). "Thus, the role of netrin-1 in those tumor tissues with reduced netrin-1 expression might exert a different functional pattern from those with increased expression of netrin-1." (PMID 35974411, 2022). "Hence, UNC5H receptors could serve as conditional tumor suppressors depending on the presence of netrin-1, theoretically providing two ways to impact tumorigenesis." (PMID 32902412, 2020). "Furthermore, NTN1 located on hypoxic tumor areas that contain motile GBM stem-like cells." (PMID 28069038, 2017). "Moreover, we investigated the localization of NTN1 in the tumor tissues." (PMID 28069038, 2017). "However, it is not known whether the current preclinical anti-netrin-1 approaches, which mainly focus on trapping external netrin-1 to induce tumor cell apoptosis, can be modified in a way to block also the intracellular action of netrin-1." (PMID 24647424, 2014). "Thus, NTN1 expression confers resistance to apoptosis, thus, enhancing tumor cell survival." (PMID 21789787, 2011). "In endometrial cancer models, pharmacologic blockade of Netrin-1 using the monoclonal antibody NP137 induces apoptosis, suppresses EMT, and reduces tumor burden in both preclinical and early-phase clinical settings." (PMID 41009819, 2025). "Despite the appropriate expression of Netrin-1 in PXB cells, it was expressed at a low level in tumor cells; therefore, we established Dox-inducible Netrin-1-overexpressing HepG2-NTCP-YFP cells." (PMID 41406170, 2025). "We validated that Ntn1 cKO reduced the expression of Zeb1, Vim, and Sox9 in KPC tumor cells, using qRT-PCR of FACS-sorted tdtomato-labeled tumor cells from Rosa26-LSL-tdtomato; KPC or KPCN mice." (PMID 40777309, 2025). "Netrin-1 facilitates EMT through the PI3K/AKT and ERK pathways, which promote the invasion, migration, and VM of tumor cells, thereby enhancing the metastatic potential of NSCLC cells." (PMID 40723793, 2025). "The molecular mechanism investigation revealed that NTN1 significantly enhanced the immunosuppressive function of MDSCs through A2BR on MDSCs, thus promoting the development of tumours." (PMID 38546656, 2024). "Related experiments showed that NTN1 and NTN4 were highly expressed in NB cell lines and tumour tissues and were positively correlated with poor prognosis." (PMID 38546656, 2024).